ENSG00000252425
Gene: Small nucleolar RNA gene on chromosome 15 (34,597,458 to 34,597,558, reverse strand). Ensembl gene ENSG00000252425.
Homologues: Paralogues in human: SNORA18 (76% identical).